ETS1 (ETS proto-oncogene 1, transcription factor)
Diseases named in the same sentence as ETS1 in open-access papers (continued):
Sharing a sentence is not in itself a finding about the gene and the disease.
breast carcinoma (continued). "Next, we tested whether differential expression of NFATc2 or NF-κBs has any correlation with Ets1 expression in human breast cancer specimens by analyzing The Cancer Genome Atlas (TCGA) database that provide unbiased large-scale transcriptome data for various human cancer." (PMID 30467308, 2018). "Taken together, these data suggest that the Ets1-dependent estradiol sensitization of breast cancer cells and tumors may be partially due to the ability of Ets1 to cooperate with ERα and nuclear receptor coactivators to stimulate transcriptional activity of estrogen-dependent genes." (PMID 23874775, 2013). "Because MCF7 cells are a well characterized, stable epithelioid breast cancer cell line expressing estrogen, androgen, progesterone and glucocorticoid receptors, but not Ets1 and display increased clonogenicity upon Ets1 expression, we selected them for further analysis." (PMID 23874775, 2013). "Subsequently, we sought to verify the roles of ETS1 and MMP3 in dasatinib-mediated inhibition of breast cancer progression." (PMID 41462902, 2025). "Thus, ETS-1 expression may serve as a valuable prognostic biomarker for breast cancer." (PMID 40181983, 2025). "Here the authors report that ETS1-driven caspase-1 expression is a feature of TNBC and is required for IL1β-mediated macrophage recruitment and breast cancer growth." (PMID 39353903, 2024). "Briefly, SRC-1 promotes the transcriptional activityof several transcription factors, including HOXC11, PEA3, AP-1, HIF1α, c-FOS, Ets1/2, and STAT1/3, in breast cancer." (PMID 38553750, 2024). "ETS1 is reported to up-regulate PARP1 in Ewing sarcoma and ovarian cancer, while ETS1 and ETS2 repress BRCA1 in breast cancer." (PMID 36814284, 2023). "PTPN18 WT decreased ETS1 stability and inhibited breast cancer metastasis, but two cytoplasmic PTPN18 mutants, mC-NLS and mPY-NLS, stabilized ETS1 and restored the metastatic ability by spatiotemporal regulation." (PMID 35982039, 2022). "Recently, we found that ELF3 is highly expressed in the luminal subtype of breast cancer cells, and represses upregulation of ZEB1/2 by ETS1 in such cells." (PMID 33712555, 2021). "Circular RNA hsa_circ_001783 sponges miR-200c-3p in breast cancer, which leads to the upregulation of miR-200c-3p target genes ZEB1, ZEB2, and ETS1." (PMID 34439151, 2021). "To elucidate how ETS1 affects tumorigenesis of BRCA, we tested the effects of knockdown of ETS1 on tumorigenicity of breast cancer cells." (PMID 32477936, 2020). "miR-125b is reported to play tumor suppressive roles via targeting KIAA1522, ETS1, and SNAI1 in breast cancer." (PMID 31750242, 2019). "Treatment of the transcription inhibitor actinomycin D abolished PMA/Ionomycin induced Ets1 expression, indicating that Ets1 expression is regulated at the transcriptional level in the metastatic MDA-MB-231 breast cancer cells." (PMID 30467308, 2018). "Correlation of ETS1 with MET and TGFBR2 was observed as well in breast cancer tissue using the TCGA breast cancer dataset." (PMID 30004628, 2018). "The transcriptional activity of ETS-1 is regulated by some co-regulators, such as SRCs (steroid receptor co-activators) and AIB-1 (amplified in breast cancer 1)." (PMID 29312607, 2017). "Human breast cancer cells MDA-MB-231, which lacks the ERα but normally expresses ETS-1, were co-transfected with the EBS-Luc, ERα or empty vector." (PMID 26122040, 2015). "In this study we investigated the effects of ETS1 on adriamycin resistance in MCF-7/ADR cells, which are typical multidrug-resistant human breast cancer cells that were selected by exposure to adriamycin." (PMID 24602286, 2014). "In this study, we confirmed that ETS1 mRNA and protein are overexpressed in adriamycin-resistant human MCF-7/ADR breast cancer cells." (PMID 24602286, 2014). "Breast cancer cells are more resistant to anti-cancer drugs, such as doxorubicin or paclitaxel, due to high expression of MDR1 and Ets-1." (PMID 23405229, 2013).
breast carcinoma (continued). "The Ets-1 knockdown cell line MDA-Ets1KD was generated, because the aggressive MDA-MB-231 breast cancer cell line expresses Ets-1 in abundance, where Ets-1 expression is decreased to 22.7% of parental levels." (PMID 24280356, 2013). "The ETS1 overexpression promotes malignancy through HGF/Met-mediated motility, which allows breast cancer cells to bypass the requirement of promigratory signals supplied by the environment (such as fibronectin) for invading." (PMID 18941460, 2008). "In the present study, we demonstrated that the enhancement of invasive phenotype of breast cancer cells by PRDX6 was accompanied by upregulation of MMP-9 and Ets-1 expression and downregulation of TIMP-2 expression." (PMID 17980029, 2007). "Furthermore, breast cancer exhibited high SP100 expression with favorable outcomes, mediated by ETS1 repression and IFN-α modulation, highlighting a tumor-suppressive role for SP100 distinct from other cancers." (PMID 41188771, 2025). "In this study, we examined the effect of four PARPi, PJ‐34, ABT‐888, olaparib, and rucaparib in two breast cancer cell lines without BRCA mutation, Ets‐1‐expressing MDA‐MB‐231, and Ets‐1‐non‐expressing MCF‐7." (PMID 39778077, 2025). "ETS1 and MMP-1 are co-expressed in skin angiosarcoma, whereas ETS1 is co-expressed with MMP-1 and MMP-9 in ovarian carcinoma cells and in stromal fibroblasts of breast carcinoma." (PMID 39941022, 2025). "Since ETS1 and MYBL2 as well as EIF4EBP1 are overexpressed in other cancer entities, for instance in colorectal cancer or breast cancer, these transcription factors might also regulate EIF4EBP1 expression in cancers outside the CNS." (PMID 35228525, 2022). "Ets1 activates the ZEB1 promoter and induces endogenous ZEB expression in breast cancer cells." (PMID 35451213, 2022). "Ets-1 was also shown to bind to the CCR7 promoter and there was a good correlation between Ets-1 expression and CCR7 expression in basal-type breast cancer cell lines, such as MDA-MD-231, suggesting that Ets-1 is a likely mediator of CCR7 effects including cancer cell migration." (PMID 35203305, 2022). "Using cell lysates obtained from the breast cancer cell line MDA-MB-231 as a positive control, the antibody was found to specifically detect phospho-ETS1 Thr265, Ser269 both in the absence and presence of the control peptide (i.e., without phosphorylated residues)." (PMID 34023818, 2021). "Compared with less metastatic cells (MCF-7), metastatic breast cancer cells (MDA-MB-231) have relatively open chromatin structure on the CRE, which facilitates direct binding of NFATc2 and NFKB1/RELA to enhance Ets1 expression and invasiveness of metastatic breast cancers, accordingly." (PMID 30467308, 2018). "Compared with the less metastatic breast cancer cells, metastatic breast cancer cells (MDA-MB-231) show open chromatin configurations in the CRE, which facilitates direct binding of NFATc2 and/or NFKB1/RELA complex to trans-activate Ets1 transcription." (PMID 30467308, 2018). "Based on these observations, we hypothesized that down-regulation of ETS1 using siRNAs would result in heightened drug sensitivity and reverse MDR in breast cancer cells." (PMID 24602286, 2014). "Deep sequencing of mRNA isolated from a panel of breast cancer cell lines found that direct comparison of transcripts from ER positive lines and ER negative lines identified a 922-fold elevation in ETS1 expression in the ER negative lines." (PMID 23874775, 2013). "In fact, RT-qPCR analysis of multiple Ets factors in human breast cell lines showed that ETS1 expression was undetectable in ERα positive breast cancer lines, but expressed in ERα negative lines." (PMID 23874775, 2013). "In addition, glutathione S-transferase (GST) pull-down assay demonstrated that HIF-2α physically interacts with ETS1, and immunoprecipitation analysis showed that HIF-2α forms a complex with Elk1 in MCF7 (breast cancer) and 786-O (renal cell carcinoma) cells." (PMID 23840432, 2013).
breast carcinoma (continued). "Three of the four cell lines tested exhibited increased colony formation in response to Ets1 expression; however, the BT-474 cell line, the only one of these ERα positive, luminal breast cancer lines that expresses ErbB2, did not." (PMID 23874775, 2013). "Clonogenic assays were performed with the BT-474, MCF7, T-47D and ZR-75-1 ER-positive, Ets1-negative human breast cancer cells after transient transfection with Ets1 or empty vector." (PMID 23874775, 2013). "Interestingly, several of the elements identified in our computational analysis are bound by transcription factors such as STAT1, STAT3, STAT5, ETS1, PAX and E2F, which play important roles in mammary function and in breast cancer." (PMID 21655091, 2011). "ETS-1 is a prognostic marker of breast cancer, independent of other tumor markers such as nodal status, tumor size, histological grade, or estrogen receptor status." (PMID 18958307, 2008). "siRNAs against ETS1 or negative control siRNAs was transfected to MCF-7/ADR breast cancer cells." (PMID 24602286, 2014). "Our study made the novel observation that the oncogenic transcription factor Ets-1 is a critical mediator of NOS2 and NO-induced signaling in breast cancer and thus, this study provides a molecular mechanism that at least partly explains the oncogenic effects of NO in ER- breast cancer." (PMID 22971289, 2012). "Similarly, levels of Ets-1 mRNA were not significantly different in fibroadenomas and primary breast carcinomas." (PMID 15365563, 2004). "Furthermore, our data showing that NO results in a MEK/ERK/Ets-1 signaling cascade in ER-/HER2+ SKBR3 cells suggest that high NOS2 expression and NO signaling may induce proliferative and aggressive phenotypes in HER2+ breast cancer." (PMID 22971289, 2012). "However, ETS-2 has also been implicated in prostate cancer and together with other factors including ETS-1, SRC-1 (v-src avian sarcoma [Schmidt-Ruppin A-2] viral oncogene homolog), AIB-1 (nuclear receptor coactivator 3) and NcoR (nuclear receptor co-repressor), breast cancer." (PMID 18958307, 2008). "In breast cancer and OSCC cells, expression profiles of ZEB1/2 and Snail are not positively correlated with each other and those of Ets1/2 levels." (PMID 35451213, 2022). "In MDA-MB-231 breast cancer cells but not MCF-7 cells, overexpression of the p42 form of Ets-1 was found to reduce cell survival." (PMID 15365563, 2004).
hepatocellular carcinoma (61 papers, 2012 to 2025). A malignant tumor that arises from hepatocytes. "Ets1 has been associated with various conditions, including hepatocellular carcinoma, healthy aging, congenital heart defects, and arthritis." (PMID 37672148, 2024). "Further, ETS1 is required for resistance to sorafenib in hepatocellular carcinoma by disrupting mitochondrial ROS, leading to increased invasion." (PMID 40356520, 2025). "In other types of cancer, such as hepatocellular carcinoma, ETS1 has been found to act as a tumor suppressor and inhibit tumor cell proliferation by targeting RYBP." (PMID 38649363, 2024). "For example, ETS1 promotes resistance to sorafenib in hepatocellular carcinoma by regulating ferroptosis via the miR-23a-3p/ACSL4 axis." (PMID 37490064, 2023). "External validation confirmed positive correlations for FAP and angiogenesis receptors FLT1, KDR, and KIT as well as HIF1A and ETS1 in hepatocellular carcinoma but also in metastatic prostate cancer (Dream Team cohort)." (PMID 36672341, 2023). "Meanwhile, WTAP plays an important role in the progression of hepatocellular carcinoma by affecting the epigenetic modifications of ETS1." (PMID 35592424, 2022). "WTAP increased hepatocellular carcinoma cell proliferation and tumor growth in vitro and in vivo via the m6A-HuR-dependent epigenetic silencing of ETS1 in vitro and in vivo." (PMID 35860262, 2022). "Consistent with this notion, overexpression of full-length or extracellular domain-truncated syndecan-1 in human hepatoma cell lines resulted in cell differentiation via downregulation of the transcription factors Ets-1 and AP-1." (PMID 33801718, 2021). "miR-139-5p can inhibit aerobic glycolysis, cell proliferation, migration, and invasion in hepatocellular carcinoma via regulating ETS1." (PMID 33954179, 2021). "ETS1, as a transcription factor, is frequently reported to promote cancer progression, such as hepatocellular carcinoma." (PMID 34378314, 2021). "In renal carcinoma and glioma, ETS1 promotes cell proliferation by up-regulating TGFα expression; in hepatocellular carcinoma, ETS1 promotes cell proliferation by activating the expressions of cyclin E and cyclin-dependent kinase 2 (CDK2)." (PMID 34889689, 2021). "WTAP expression was up-regulated in hepatocellular carcinoma; WTAP-mediated m6A modification led to epigenetic silencing of the tumor suppressor gene ETS1, and promoted the progression of hepatocellular carcinoma by regulating the cell cycle." (PMID 33363011, 2020). "To confirm the implication of downregulated Ets-1 in the partial differentiation and suppressed proliferation of hepatoma cells overexpressing syndecan-1, we knocked down Ets-1 expression by miRNAs." (PMID 32977498, 2020). "In addition, WTAP knockdown led to a G2/M phase block in hepatocellular carcinoma via the ETS1-p21/p27 axis, promoting apoptosis in tumor cells." (PMID 36139062, 2022). "Similarly, previous research has identified ETS1 as a proto-oncogene in various cancers, including hepatocellular carcinoma, colorectal cancer, and cervical cancer malignancy." (PMID 35463077, 2022). "ETS1 silencing rescued the inhibitory effect of WTAP knockdown on the growth and viability of hepatocellular carcinoma cells." (PMID 36139062, 2022). "For example, the available literature reports that in hepatocellular carcinoma, WTAP can promote the degradation of ETS1 through the m6A-way, which in turn promotes the progression of hepatocellular carcinoma." (PMID 35733918, 2022). "It has been published that exposure of hepatoma cell lines to HGF induced transcription of ETS1 and, subsequently, MMPs, whereas silencing of ETS1 downregulated production of MMPs." (PMID 32977498, 2020). "Recent study indicated that miR-377 targeted oncogenic ETS1 gene and functioned as a tumor suppressor in CCRCC, and miR-377 inhibited TIAM1 expression and repressed cell growth and metastasis in hepatocellular carcinoma." (PMID 27351135, 2016).
hepatocellular carcinoma (continued). "However, recent studies described novel ETS1 inhibitors and their role in antitumor activity against hepatitis B/C virus (HBV/HCV) induced hepatocellular carcinoma, lymphoma and vessel regression." (PMID 40198713, 2025). "As an adaptor, WTAP is overexpressed in many cancers and serves as an oncogenic protein that can down-regulate the c-Myc, HMBOX1, and ETS1 mRNAs in an m6 A-mediated manner, enhancing the proliferation and metastasis of AML, osteosarcoma, and hepatocellular carcinoma (HCC)." (PMID 40483535, 2025). "Conversely, mir-193b showed a negative correlation with ETS1 mRNA in hepatocellular carcinoma (HCC) suggesting that miR-193b mediates ETS1 mRNA degradation." (PMID 40565345, 2025). "ETS1 could interact with the pregnane X receptor (PXR) to promote its accumulation in the nucleus, thus accelerating sorafenib clearance from hepatoma cells." (PMID 33585247, 2020). "In hepatocellular carcinoma, miR-139-5p inhibits the expression of glycolytic genes, hexokinase 1 (HK1) and 6-phosphofructo-2-kinase/fructose-2,6-biphosphatase 3 (PFKFB3) expression by directly targeting the ETS1 transcription factor." (PMID 32564010, 2020). "Moreover, miR-193b-3p was able to regulate proliferation, migration, and invasion in human hepatocellular carcinoma cells by suppressing CCND1 and ETS1." (PMID 31262974, 2019). "Previous studies have demonstrated that miR-377 served as tumor suppressor to regulate the progression of lung cancer, cervical cancer, glioma, gastric cancer, esophageal cancer, hepatocellular carcinoma cells and clear cell renal cell carcinoma by targeting CD133, VEGF, Bcl-xL and ETS-1." (PMID 31746333, 2019). "In hepatocellular carcinoma (HCC), METTL3 suppresses SOCS2 expression in a YTHDF2-dependent manner, while WTAP reduces ETS1 mRNA levels through the m6A mechanism, collectively promoting cell cycle progression and tumor proliferation." (PMID 41446042, 2025). "Our previous results confirmed that the differentiation of hepatoma cell lines after syndecan-1 transfection acted together with the changes of an HS pattern to a more sulfated one, as indicated by HS-specific antibodies, capable of interfering with the promoter activation of AP1 and Ets1." (PMID 33801718, 2021). "In conclusion, our study demonstrates that miR-324-5p suppresses hepatocellular carcinoma cell invasion by attenuate the expression and activity of MMP2 and MMP9, subsequently counteracting ECM degradation, through post-transcriptionally downregulating ETS1 and SP1." (PMID 26177288, 2015). "We propose that the NO/Ets-1 signaling axis first described here may promote disease progression in other tumors that overexpress NOS2, such as glioma and melanoma, and tumors with impaired SNO metabolism, such as lung and hepatocellular carcinoma." (PMID 22971289, 2012).